TERT (telomerase reverse transcriptase)
Diseases named in the same sentence as TERT in open-access papers (continued):
Sharing a sentence is not in itself a finding about the gene and the disease.
glioma (continued). "An increasing number of molecular biomarkers, such as TERT promoter mutation, IDH1/2 mutation and 1p/19q co-deletion, have been used in clinic of glioma." (PMID 33557829, 2021). "In recent years, the identification of molecular alterations (including IDH, TERT promoter mutation, MGMT methylation, and 1p/19q codeletion) associated with the prognosis of glioma." (PMID 33777772, 2021). "Several GWAS and GWAS meta‐analyses have identified 20q13.33 as a risk locus, especially its association with isocitrate dehydrogenase 1 (IDH1) wild‐type or TERT (telomerase reverse transcriptase)‐only gliomas." (PMID 33169458, 2021). "MGMT promoter methylation was associated with a superior OS in both TERT-mut (HR = 0.29; 95% CI = 0.21–0.39; I2 = 44%) and TERT-wt gliomas (HR = 0.54; 95% CI = 0.39–0.74; I2 = 19%)." (PMID 32957941, 2020). "TERTpmut disrupt the tight transcriptional suppression of TERT in somatic cells resulting in increased TERT expression and telomerase activity in vitro in glioma." (PMID 31960234, 2020). "A meta-analysis of the Telomerase Reverse Transcriptase (TERT) gene, a component of telomerase which is linked to immortalisation of cancer cells, highlighted it as being an important biomarker for gliomas." (PMID 32041307, 2020). "The Kaplan–Meier survival curves also showed that both TERT promoter mutation and 1p/19q codeletion were strongly associated with a favorable prognosis in IDH-mutated gliomas." (PMID 33228806, 2020). "In the present study, we summarized the clinical and basic molecular pathological characteristics of 83 patients with spinal cord astrocytomas, thus revealing the prognostic value of the BRAF V600E and TERT promoter mutations in grade II and III gliomas." (PMID 32228694, 2020). "High BACE2 expression was related to wild‐type IDH1 in glioma patients, while low BACE2 expression was associated with other features, including MGMT promoter methylation, 1p/19q codeletion, TERT loss and ATRX mutation." (PMID 31856384, 2020). "For example, high-grade gliomas are associated with risk variants in RTEL1, CDKN2B, and TERT, while low-grade gliomas with IDH mutation-1p/19q codeletion are associated with risk variants in CCDC26 and PHLDB1 regions." (PMID 31968687, 2020). "This modification significantly reduced TERT transcription and induced the senescence of gliomas cells, which presented the opposite results to our study for deciphering transcriptional control." (PMID 32438712, 2020). "In recent years, in order to improve the treatment effect of glioma, some glioma subtypes have been identified based on molecular genetic features, such as IDH mutation, TERT promoter, and 1p/19q codeletion." (PMID 32272554, 2020). "The TERT genotype is not only a vital prognostic and predictive biomarker for glioma, especially for HGG, but also a promising indicator for the sensitivity of GBM to radiotherapy and temozolomide." (PMID 32509858, 2020). "For the purpose of investigating the impact of TERT promoter mutation and 1p/19q codeletion on survival in IDH-mutated glioma cases, the patient cohort was divided into four groups dictated by TERT and 1p/19q statuses." (PMID 33228806, 2020). "The association between LGALS3 and glioma clinically relevant diagnostic/molecular markers (IDH, 1p19q, ATRX, MGMT, and TERT) was examined using the Chi-Squared (χ2) test." (PMID 32528967, 2020). "The most recent cIMPACT update on IDH-WT infiltrating gliomas recommends upgrading of infiltrating gliomas bearing EGFR amplification and/or 7 gain/10 loss and/or TERT mutation as glioblastoma equivalents." (PMID 33059718, 2020).
glioma (continued). "It is enriched in elderly patients, with approximately 40% having grade II/III glioma, suggesting TERT’s correlation with shorter overall survival as a key pathological player and therapeutic target." (PMID 33102518, 2020). "Frequent alterations in the promoter of the telomerase reverse transcriptase (TERT) gene have been described across several cancers including glioma." (PMID 32513296, 2020). "Our study demonstrated that TERT promoter mutations showed contradicting effects in MGMT-meth and MGMT-unmeth gliomas." (PMID 32957941, 2020). "For IDH-WT glioma grading, the cIMPACT update 3 recommends the assessment of EGFR amplification, combined chromosomes 7p gain/10q loss, and TERT promoter mutation, which are established predictors of poor outcome, regardless of histology ⁠." (PMID 33059718, 2020). "The aim of this study was to investigate the interplay among IDH1, TL, ATRX and TERT/ALT using a newly developed distinctive methodology that allowed determination of glioma cell-specific telomere length (CS-TL) on a single cell level." (PMID 31960234, 2020). "Up to now, a large number of researches have explored the role and value of TERT in glioma, which demonstrated that 80% of the TERT promoters in the primary GBM have mutated." (PMID 32509858, 2020). "TERT promoter mutations and ATRX alterations have been described across glioma subtypes in a mutually exclusive pattern." (PMID 33747896, 2020). "Some molecular genetic features including IDH1/2 mutation, MGMT promoter methylation, co-deletion of 1p/19q, TERT loss, and ATRX mutation have been reported to be associated with favorable prognosis in gliomas." (PMID 30658672, 2019). "Three of these glioma risk loci (TERC, TERT, and RTEL1) contain genes involved in telomere maintenance." (PMID 30625996, 2019). "Univariate analysis showed that high NLR predicted shorter OS in lower-grade glioma groups defined by IDH and TERT mutations (P = 0.009), IDH mutation only (P = 0.047), TERT mutation only (P = 0.005), and in the triple-negative group (P = 0.005)." (PMID 31444316, 2019). "For example, gliomas more frequently re-express TERT, but about 80% of ALT-positive pediatric high-grade gliomas are ATRX-deficient." (PMID 30970016, 2019). "For lower-grade glioma cases (n = 392), 103 (26.3%) were triple-positive, 19 (4.8%) had both IDH and TERT mutations, 100 (25.5%) had IDH mutation only, 48 (12.24%) had TERT mutation only, 78 (19.9%) were triple-negative, and 44 (11.2%) had other combinations." (PMID 31444316, 2019). "TERT promoter and ATRX mutations were found to be the most recurrent somatic events which led to glioma associated lengthening of telomeres." (PMID 31157162, 2019). "Previous studies have mentioned that the patterns of IDH1/2 and TERT were involved in glioma classification." (PMID 31690770, 2019). "Summarizing, we prove that telomerase re-activation based on a mutant TERT promoter sequence in BRAFV600E-mutant glioma is driven by oncogenic BRAF signaling predominantly via downstream activation of ETS-factors." (PMID 31391125, 2019). "Taken together, our data suggest that apart from the demonstrated TERT promoter activating properties, ETS-factors appear to play an important role in tumor biology of BRAFV600E-mutated glioma." (PMID 31391125, 2019). "TERT mRNA was constitutively downregulated by dabrafenib or vemurafenib in double-mutant glioma models only." (PMID 31391125, 2019). "Following the reclassification of gliomas according to the 2016 WHO classification, we investigated the role of TERT promoter mutations, EGFR amplification, PTEN deletion and MGMT promoter methylation in molecular glioma subgroups." (PMID 31623593, 2019).
glioma (continued). "In summary, our study corroborates the prognostic significance of glioma subtypes based on 1p/19q codeletion and IDH and TERT promoter mutations in a large Chinese cohort." (PMID 31444316, 2019). "This will enhance the translation of a number of key genes associated with malignant progression of gliomas, such as c-Myc, NRF2, TERT, POLR1A, and POLR2A." (PMID 30936423, 2019). "In line with previous reports from our group concerning meningioma, also glioma cell models harboring mutant TERT promoters were hypersensitive towards YK-4-279 treatment and YK-4-279 distinctly reduced TERT mRNA expression." (PMID 31391125, 2019). "For Grade IV glioma cases (n = 181), 8 (4.4%) had IDH mutation only, 107 (59.1%) had TERT mutation only, and 66 (36.5%) were triple-negative." (PMID 31444316, 2019). "Recently, glioma is also classified into three types based on its molecular markers: 1p/19q deletion, IDH mutation and TERT promoter mutation." (PMID 31850228, 2019). "Then, we also analyzed the impact of TERT promoter mutations, PTEN deletion, EGFR amplification and MGMT promoter methylation in diagnosis, prognosis and response to therapy in glioma molecular subgroup." (PMID 31623593, 2019). "A population-based study that analyzed 3 molecular markers (1p/19q, IDH1/2, and TERT promoter) stratified grade II and III gliomas into five molecular subgroups independently associated with clinical outcomes." (PMID 31788444, 2019). "Collectively, these results indicate that c-Myc, NRF2, and TERT can transcriptionally regulate NAF1 in glioma cells." (PMID 30936423, 2019). "In vitro, BRAFV600E/TERT promoter double-mutant glioma cells showed exceptional sensitivity towards BRAF-targeting agents." (PMID 31391125, 2019). "We analyzed co-occurrence of BRAFV600E and TERT promoter mutations in our clinical data (n = 8) in addition to published datasets (n = 103) and established a BRAFV600E-positive glioma cell panel (n = 9) for in vitro analyses." (PMID 31391125, 2019). "Accordingly, in contrast to TERT promoter wild-type glioma, ETS-factor inhibition by YK-4-279 reduced TERT mRNA expression in double-mutant cell models whereas ETS1 expression was more variable." (PMID 31391125, 2019). "TERT promoter mutations have been found to influence the transcriptional regulation of the TERT gene and were identified in several cancers including melanoma, NMSCs, bladder cancer and glioma." (PMID 30884806, 2019). "Common inherited variants of telomere related genes, such as TERC, TERT, and rare POT1 mutations have been found to be associated with higher risk of developing gliomas." (PMID 31157162, 2019). "Further studies revealed that NAF1 was transcriptionally regulated by c-Myc, NRF2, and telomerase reverse transcriptase (TERT), which are the key molecules associated with malignant progression of gliomas." (PMID 30936423, 2019). "In conclusion, the pretrained CNN texture features capture the information of IDH and TERT genotypes in grade II/III gliomas better than the conventional radiomic features." (PMID 31889117, 2019). "To model the genomic consequences of ATRX deficiency in a glioma-relevant cellular context, we performed shRNA-mediated ATRX knockdown in TERT and E6/E7-transformed NHAs." (PMID 30808951, 2019). "In turn, high PLR predicted shorter OS in the IDH mutation only (P = 0.014) and TERT mutation only (P = 0.001) groups, while high MLR was associated with shorter OS in gliomas with IDH and TERT mutations (P = 0.006)." (PMID 31444316, 2019). "Fortunately, recent studies have identified somatic mutation in the isocitrate dehydrogenase 1 and 2 (IDH 1 and 2) as well as Telomerase Reverse Transcriptase (TERT) promoter genes which present over 80% of glioma." (PMID 30803189, 2019).
glioma (continued). "In contrast, about half of all pediatric high grade gliomas (PHGGs) is positive for ALT, and a smaller subgroup of about 23% has activated telomerase, with TERT promoter mutations and chromothripsis being quite uncommon." (PMID 31757062, 2019). "Hotspot mutations (c.-124bp G > A and c.-146bp G > A) in the promoterregion of the TERT gene have been recently described in severaltypes of solid tumors, including glioma, bladder, thyroid, liver and skinneoplasms." (PMID 29473934, 2018). "Gliomas are heterogeneous, hence to investigate the relationship between risk SNPs and glioma subtype we analysed 1659 tumours profiled for IDH mutation, TERT promoter mutation and 1p/19q co-deletion." (PMID 29460007, 2018). "Together, we developed a novel TERT-specific antibody, and it is sensitively and specifically applicable to immunohistochemistry for TERT in human glioma tissue." (PMID 29693015, 2018). "It would be thus critical to examine the expression level of TERT in tumors in addition to its mutational status, and sensitive and specific methods are urgently needed to examine TERT protein expression for the assessment of TERT biology in gliomas." (PMID 29693015, 2018). "Surprisingly, however, an increase in TERT protein expression was detected across all types of gliomas including tumors with wildtype TERT, and the level of TERT expression was different even among the TERT-mutant gliomas such as oligodendrogliomas and GBMs." (PMID 29693015, 2018). "In order to evaluate the expression of TERT protein in human glioma tissue, we developed and screened novel anti-hTERT monoclonal antibodies that will be applicable to human tissue sections." (PMID 29693015, 2018). "IDH wild-type high grade gliomas with 7p gain, 10q loss, EGFR amplification and TERT promoter mutation were considered as GBM (corresponding to WHO grade IV) (n = 146)." (PMID 29720725, 2018). "The hot spot nucleotide changes − 124G>A and − 146G>A in TERT promoter have been detected at high frequency in cancers of internal organs, such as bladder cancer, hepatocellular carcinoma, thyroid cancer, and gliomas." (PMID 29562930, 2018). "Re-analysis of previously published samples reclassified according to WHO 2016 criteria demonstrated that approximately 75% of diffuse IDH-wildtype gliomas are TERT promoter mutant." (PMID 29616301, 2018). "An example is the significant worse overall survival of patients with a grade II glioma with an IDH-wildtype tumor with gain of chromosome 7 and loss of chromosome 10 or with TERT mutations compared to those with an IDH-wildtype tumor without these lesions." (PMID 30470264, 2018). "In this study, we developed a TERT-specific antibody applicable to human tissue and examined the expression of TERT in a series of glioma samples." (PMID 29693015, 2018). "It allows in one run the molecular assessments required for the WHO classification of diffuse gliomas, including the recent recommendations to assess copy number alterations of chromosome 7 and 10, and of the TERT promoter region in IDHwt lower grade glioma." (PMID 30470264, 2018). "Among these groups, IDH mutant only and TERT mutant only tumors are the most common and comprise about 75% of adult glioma patients." (PMID 28184256, 2017). "Higher glioma tumor grade was associated with increased mdNLR values, but mdNLR scores were similar among cases whose tumors contained IDH1 vs TERT promoter mutation." (PMID 28184256, 2017). "Some molecular genetic features including IDH1/2 mutation, MGMT promotor methylation, codeletion of 1p/19q, TERT loss, and ATRX mutation have been reported to be associated with favorable prognosis in gliomas." (PMID 29110682, 2017). "For example, evidence shows that classification of all infiltrating gliomas based on IDH, 1p/19q, and the mutational status of the TERT promoter yields clinically relevant subclasses." (PMID 29312129, 2017).
glioma (continued). "A classification system based on these three parameters yields five categories (accounting for >97% of infiltrating gliomas) with TERT status permitting further refinement of prognostics." (PMID 29312129, 2017). "The assay allows the concomitant evaluation of key markers of glioma characterization, comprising 1p/19q LOH status, and IDH and TERT mutations, conceivably in 2 working days, with limited cost per sample (about 80 euro per sample)." (PMID 28915660, 2017). "In our study, we used a panel composed of IDH1/1p19q/TERT which is worldwide recognized in the precise diagnosis of glioma to demonstrate the anatomic distribution of different molecular subsets." (PMID 28915860, 2017). "Noninvasive prediction of other important glioma biomarkers, such as 1p19q and TERT, will be considered for future work." (PMID 28710497, 2017). "In a cohort of 18 lower grade gliomas, in addition to the TERT promoter, OncodriveFML identifies the promoter of SPN with a highly significant FM bias." (PMID 27311963, 2016). "Decreased expression of both G6PD and TKT was observed in glioma cells upon transfection with TERT dominant-negative construct or siRNA-mediated knock-down of TERT." (PMID 27148686, 2016). "The non-canonical pathway has been shown to have distinct functions in oncogenesis, such as driving growth and invasion of mesenchymal glioma and regulation of the mutant C250T TERT promoter." (PMID 27732951, 2016). "Collectively, TERT promoter mutations and long RTL are not only prognostic factors for poor clinical outcomes, but also the predictors of radiotherapy resistance in gliomas." (PMID 26556853, 2016). "In this study, we tested the effect of TERT promoter mutations and the RTL on outcomes of radiotherapy and chemotherapy in a cohort of gliomas." (PMID 26556853, 2016). "In this study, we sought to investigate TERT promoter mutations and relative telomere length (RTL) in a large cohort of Chinese patients with well-characterized gliomas, and explore their associations with clinical outcomes of these patients." (PMID 26556853, 2016). "On subsequent multivariate analysis, however, only RT was an independent prognostic factor in TERT promoter mutated WHO grade II and III gliomas." (PMID 26314843, 2015). "At that time, we also reported in a separate study utilizing a different cohort of WHO grade II to IV gliomas that IDH and TERT promoter mutations categorized four distinct subgroups in grade III and grade IV gliomas." (PMID 26314843, 2015). "Recent studies have identified recurrent mutations in the promoter region of telomerase reverse transcriptase (TERT) in gliomas." (PMID 26314843, 2015). "The combined mutational status profile of the TERT promoter and IDH reflected the survival in different histological sub-types of gliomas." (PMID 25797251, 2015). "As for TERT promoter mutated and wild-type WHO grade II and III gliomas, univariate analysis showed that RT and CHT were prognostic factors, significantly influencing PFS in the two subgroups." (PMID 26314843, 2015). "Increased telomerase activity is one of the hallmarks of human tumors and TERT is frequently up-regulated in a variety of tumors including gliomas, preventing telomere shortening and inhibiting apoptosis and senescence." (PMID 26143636, 2015). "Overall, the data suggested that lower grade gliomas with IDH mutations and 1p19q co-deletions are biologically distinct and arise from a sequence of IDH mutation and 1p19q deletion, TERT/PI3 kinase activation, and NOTCH1 inactivation." (PMID 26244119, 2015). "IDH wt/TERT mut gliomas were previously shown to exhibit a dismal prognosis and were most prevalent in primary GBM." (PMID 26314843, 2015).